GSDMD (gasdermin D)
Diseases named in the same sentence as GSDMD in open-access papers (continued):
Sharing a sentence is not in itself a finding about the gene and the disease.
cancer (continued). "Meanwhile, GSDMD and GSDMB were differentially expressed in most tumors, and all evidence supported their involvement in the induction of the pyroptosis process in cancer, which also increased the predictive value of UCEC." (PMID 35574367, 2022). "In cancer, pyroptosis has been shown to be triggered by almost all signaling pathways in which GSDME, GSDMD, GSDMC, or GSDMB serve as the executors." (PMID 35673561, 2022). "The GSDM family includes six members, GSDMA, GSDMB, GSDMC, GSDMD, GSDME (DFNA5), and PJVK (Pejvakin, DFNB59), which can induce pyroptosis, thereby regulating the tumorigenesis of various cancers." (PMID 36505798, 2022). "The expression of selected 6 PRGs (GSDMC, GSDMD, GSDME, NLRP3, NLRC4, and IL1B) was assessed in 6 types of cancers and adjacent normal tissues." (PMID 36605187, 2022). "To assess the relevance of these findings in human cancers, we analyzed the expression correlation of MLL3 and MLL4 with GSDMD across TCGA human tumors." (PMID 36323669, 2022). "Six GSDM family genes (i.e., GSDMA, GSDMB, GSDMC, GSDMD, GSDME, and PJVK) have long been described in other fields; however, they have been rarely investigated in a pan-cancer setting." (PMID 36003332, 2022). "We found that most tumors analyzed and exhibited a certain level of GSDMs expression; however, the expression of GSDMD, GSDMB, and GSDME in pan-cancers was markedly higher than that of other genes." (PMID 36003332, 2022). "GSDMC, GSDMD, GSDME, ZBP1, AIM2, DHX9 and NLRP3 demonstrated significant amplification across cancers." (PMID 36605187, 2022). "Gasdermin D (GSDMD) is a major protein family that is related to pyroptosis and is involved in many inflammatory diseases and cancers." (PMID 34768867, 2021). "Treating human-derived macrophages with the supernatants from co-cultured CD19-CAR-T cell and cancer cells (NALM-6, Raji, or primary B leukemic cells) prompted macrophage activation of caspase-1, cleavage of GSDMD, and release of IL-6 and IL-1β." (PMID 34429144, 2021). "As GSDMD and GSDME are crucial executors of pyroptosis, here we explain the anti-cancer effects of pyroptosis by introducing the role of GSDMD and GSDME." (PMID 33665167, 2020). "There are some studies indicated that certain drugs or molecules could trigger GSDMD-mediated pyroptosis in various types of cancer, which suggested this new type of programmed cell death was involved in the pathogenesis of cancer and could be a new target in cancer management." (PMID 31616642, 2019). "More investigations are required to disclose the precise mechanisms behind GSDMD- and GSDME-mediated pyroptotic pathways, which would provide clues for cancer chemotherapy." (PMID 31492049, 2019). "GSDMD and GSDME are two important pyroptotic substrates, and they also exert other critical roles in the pathogenesis and treatment strategies exploit of cancer." (PMID 31616642, 2019). "Gene expression of GSDMA and GSDMD was frequently suppressed, and GSDMB was overexpressed in cancer cell lines and/or cancer tissue specimens." (PMID 23979942, 2013). "However, we were unable to detect cleaved GSDMD in RSL3-treated cancer cells by Western blot, while a positive control (LPS-primed THP-1 macrophages treated with nigericin) showed the predicted cleaved GSDMD bands." (PMID 40652037, 2025). "Additionally, the GSDMD pathway, triggered by NLRP3 activation, can induce pyroptosis in cancer cells, thereby suppressing cancer growth and invasion." (PMID 40718836, 2025). "The findings identify CTSS as a novel enzyme for GSDMD cleavage and establish NIR‐pyroptosis as a non‐apoptotic anticancer modality, providing a promising opportunity to overcome apoptosis resistance in current cancer therapies." (PMID 40539828, 2025). "Conversely, GSDMD is prominently enhanced in NSCLC and is thought to initiate cancer." (PMID 38584157, 2024). "The correlation between IRF2 and Gasdermin D (GSMD) expression was weak or absent in a number of cancers." (PMID 39281881, 2024).
cancer (continued). "In diverse cancer lineages (colon and lung cancer, melanoma, and leukemia), the synergistic action of TNF-α and IFN-γ can trigger the activation of a variety of signaling switches such as GSDMD, GSDME, caspase-8, and MLKL." (PMID 38553639, 2024). "Moreover, insights from the Cancer Genome Atlas highlight a relationship between GSDMD expression and CD8+ T cell indicators in primary tumors of several cancers." (PMID 38304430, 2024). "GSDMD is significantly expressed in esophageal cancer, gastric cancer, CRC, and other cancers." (PMID 39062587, 2024). "The pore-forming proteins GSDMD and GSDME, extensively studied in the GSDM family, are potential targets for combating drug resistance and contributing to the treatment and prognosis of various cancers." (PMID 38239395, 2023). "In addition to GSDMD, HsGSDME has been reported to be cleaved by both CASP3 and granzyme B at the same 267DMPD270 site, leading to the enhanced cytotoxicity of GSDME on cancer cells." (PMID 37134086, 2023). "Using The Cancer Genome Atlas (TCGA) cohorts, it has been demonstrated that GSDMD gene expression consistently correlates with markers for CD8+ T cells and that GSDMD is required for an optimal response of cytotoxic T lymphocytes to cancer cells." (PMID 37627547, 2023). "Prior results have revealed that GSDMD expression was closely related to ACC and could be used as a prognostic marker of cancer." (PMID 36911522, 2023). "It is important to consider that GSDMD-mediated pyroptosis is not the sole cell death mechanism involved in cancer." (PMID 38002346, 2023). "Nowadays, the caspase-1/GSDMD and caspase-3/GSDME pathways have attracted significant attention in pyroptosis induction, and many natural compounds have been found to activate these pathways in cancers." (PMID 38239395, 2023). "We found that the CNV in most PRGs is gained in cancer, such as GSDMC, AIM2, and GSDMD." (PMID 35008400, 2022). "The expression of GSDMD is decreased in cancer cells compared to adjacent non-cancerous cells, and this promotes the proliferation of cancer cells." (PMID 36246625, 2022). "Gasdermines (GSDMD, GSDMA, GSDMB, and GSDME) showed hypermethylation across cancers." (PMID 36605187, 2022). "In fact, GSDMC, GSDMA, GSDMD, and AIM2 were the most upregulated genes across cancers." (PMID 36605187, 2022). "We recognized that both the GSDMD and HSF1 genes are 889.264 kb apart on the same locus on 8q.24 and 15,810.256 kb downstream from one of the most overexpressed oncogenes in human cancer, the MYC chr8 (127735434-127742951)." (PMID 36497066, 2022). "Given the results of NEK7 and GSDMD in HCC, we speculated that the expression of NEK7 may regulate HCC cell pyroptosis and play a crucial role in cancer progression." (PMID 35223495, 2022). "GSDMB, GSDMC, GSDMD, GZMB, and GSDME displayed extensive CNV amplification across cancer types." (PMID 35620284, 2022). "Almost all cancer types showed substantial upregulation of GSDMC and GSDMD expression." (PMID 35922531, 2022). "In addition to GSDMD, another gasdermin protein family member (GSDME) can be cleaved by activated caspase-3, and N-terminal-cleaved GSDME can also lead to pyroptosis of cancer cells." (PMID 36428598, 2022). "The cleavage of GSDMD and GSDME in cancer cells could be induced by various therapeutic strategies, including chemotherapy drugs, molecular target therapies, or immune cell therapy." (PMID 34421915, 2021). "In addition, because of the important role of GSDMD/GSDME in the regulation of both pyroptosis and cancer therapy sensitivity, the study which focus on GSDMD/GSDME and cancer treatment sensitivity will assign a new role for pyroptosis in the future." (PMID 31616642, 2019). "In addition, the biological characteristics of gasdermin D (GSDMD) and gasdermin E (GSDME), two important pyroptosis substrates, and their prognostic role in cancer management were reviewed." (PMID 31616642, 2019).
cancer (continued). "Unlike the other GSDMs, GSDMD is widely expressed at low levels in most cancer cells." (PMID 41315764, 2026). "Our study demonstrates a CD4+ T cell–specific role of GSDMD in antitumor immunity, independent of its canonical function in pyroptosis, which may raise a new perspective for cancer immunotherapy." (PMID 40759573, 2025). "Moreover, GSDMD expression is correlated with CD8+ T cell markers in primary tumors of lung adenocarcinoma, lung squamous cell carcinoma, and melanoma cohorts of The Cancer Genome Atlas." (PMID 34858408, 2021). "Direct evidence for the crosslink between CD147 and GSDMD in cancer is lacking." (PMID 32149134, 2020). "However, the specific role of GSDMD in cancer initiation and development is still not clear." (PMID 37371484, 2023). "Gasdermin family proteins, which include GSDMA, GSDMB, GSDMC, GSDMD, and GSDME, had been studied in other fields but not in cancers." (PMID 34298833, 2021).
bacterial infection (39 papers, 2018 to 2025). "The current study enhances our understanding of the role of GSDMD in intestinal immunity, revealing that the epithelial-specific GSDMD-deficient mice have the reduced defense against intestinal bacterial infection." (PMID 38807373, 2024). "GSDMD has been implicated in NETosis during bacterial infections, where it is activated by caspase-11 or neutrophil elastase." (PMID 39250503, 2024). "Up-regulated IL-6 caused by bacterial infection inhibited GSDMD/GSDME-mediated pyroptosis by suppressing caspase-1/3 activation and thus play partly protective role in bacterial infection." (PMID 38022612, 2023). "Upregulated IL-6 caused by bacterial infection inhibited caspase-1/-3 activation to suppress GSDMD-/GSDME-mediated pyroptosis and played a partially protective role." (PMID 38022612, 2023). "In intracellular bacterial infections, however, mutation in GsdmD protein resulted in compromised bacterial clearance during L.monocytogenes infection." (PMID 31209224, 2019). "However, the specific mechanism underlying the N-terminal activity of GSDMD in protecting against intestinal bacterial infections requires future investigation." (PMID 38807373, 2024). "Bacterial infection persisting beneath the stratum corneum could lead to extensive GSDMD activity, potentially leading to a loss of the epidermis." (PMID 34821529, 2021). "Besides, GSDMD had an advantage in diagnostic specificity in bacterial infections, which was the main cause of pyroptosis." (PMID 34163438, 2021). "It has been reported that after bacterial infection and activation of the pyroptotic process, GSDMD can be released outside through the pores and deposited in the OM leading to bacterial lysis." (PMID 39714210, 2025). "Specifically, heme exposure significantly exacerbates bacterial infection induced mitochondrial damage, further amplifying GSDMD-mediated pyroptosis, RIPK/MLKL-mediated necroptosis, and caspase-mediated apoptosis." (PMID 40221420, 2025). "In our study, we demonstrated that mimicking bacterial infection by lipopolysaccharide (LPS) combined with Nigericin (Ng) effectively activates Gasdermin D (GSDMD)." (PMID 41550948, 2025). "To gain insights into the mechanisms by which GSDMD defends against bacterial infections, we first evaluated the expression of antimicrobial peptides and mucosal-related proteins within the intestinal mucosa upon theC. rodentium infection." (PMID 38807373, 2024). "During bacterial infection, GSDMD activation results in pore formation on the plasma membrane, and the release of IL-1 family cytokines, which subsequently recruit myeloid cells and elicits inflammation." (PMID 38898209, 2024). "Taken together, these findings indicate a critical protective role of GSDMD, specifically in colon epithelial cells, against intestinal bacterial infections." (PMID 38807373, 2024). "GSDMD-mediated pyroptosis has been verified to contribute to immune defence against different bacterial infections, such as Shigella, Mycobacterium tuberculosis and Streptococcus." (PMID 39334337, 2024). "By protecting intestinal epithelial cells against bacterial infection through its N-terminal segment, GSDMD emerges as a critical player in maintaining intestinal health and preventing intestinal bacterial infections." (PMID 38807373, 2024). "To investigate the role of GSDMD in host defense against intestinal bacterial infections, we usedC. rodentium to infect theGsdmd knockout and wildtype mice." (PMID 38807373, 2024). "The western-blot results showed that knockdown of β-catenin enhanced the cleavage of Caspase-1, IL-1β and GSDMD at indicated time points after pyogenic bacterial infection." (PMID 36068223, 2022). "During bacterial infection, GSDMD is necessary for cell pyroptosis, acts as a pathway for the release of danger signals such as IL-1 family cytokines, and eliminates the replicative niche of bacterial." (PMID 36589684, 2022).
bacterial infection (continued). "During primary bacterial infection, bacterial lipopolysaccharide (LPS) triggers autoproteolytic activation of caspase-4/5/11; active caspase-4/5/11 subsequently cleaves gasdermin D (GSDMD), stimulating the host immune defense." (PMID 34888685, 2022). "Studies have demonstrated that GSDMD plays a protective role in response to bacterial infections such as Brucella abortus, Legionella pneumophila, Burkholderia thailandensis, and Francisella novicida." (PMID 34011393, 2021). "Increased expression of caspase-1, secretion of IL-1β (facilitated by caspase-1), and increased substrate of GSDMD, are frequently reported in bacterial infection-related pyroptosis and sterile inflammation." (PMID 34360821, 2021). "In the context of bacterial infection, GSDMD is essential for the F. novicida-triggered AIM2 inflammasome activation, the deficiency of GSDMD increases the mouse susceptibility to the F. novicida infection." (PMID 31035661, 2019). "In this study, we demonstrated that Brucella LPS is sensed by caspase-11 and triggers GSDMD-dependent pyroptosis leading to control of bacterial infection in vivo." (PMID 30589883, 2018). "In this regard, it is reported that caspase-1 and gasdermin-D mediate pyroptosis during bacterial infection." (PMID 30248149, 2018). "Additionally, caspase-8 has been found to directly cleave gasdermin D during bacterial infection, promoting pyroptosis independently of caspase-3." (PMID 41155897, 2025). "Previous studies suggested that GSDMD plays an essential role in some bacterial infections." (PMID 36311722, 2022). "Interestingly, bacterial infection experiments further confirm that the pleural fluid GSDMD was expressed and secreted mainly by the NCs." (PMID 34163438, 2021). "In conclusion, under various kinds of pathologic status especially in the case of a bacterial infection, the level of GSDMD changed quickly and had a large variation in the amplitude, which improved the diagnostic sensitivity and the ability of an early diagnosis." (PMID 34163438, 2021). "Taken together, GSDMD mediates a variety of double-edged functions that may affect bacterial infection and inflammation in a contrasting manner." (PMID 33441602, 2021). "On the other hand, GSDMD promotes mice survival in response to certain bacterial infections." (PMID 33441602, 2021). "The essential roles of GSDMD in intracellular bacterial infection have been widely recognized." (PMID 35100869, 2021). "The GSDMD was detected in the control growth medium, which could suggest that GSDMD might be produced constitutively by THP1-Null2 cells as an inactive pro-protein crucial for the biochemical "ready to react" system in response to bacterial infection (LPS) via pyroptosis." (PMID 39714210, 2025). "The GSDMD−/− mice presented decreased IL-1β and increased Cxcl1 secretion following S. aureus infection, suggesting that upon S. aureus challenge, promotion of IL-1β production or inhibition of Cxcl1 may be the key for the protective effect of GSDMD during bacterial infection." (PMID 34011393, 2021). "Collectively, our data indicate that GSDMD and CASP7 are activated by CASP1 and induce cell death and restriction of bacterial infection." (PMID 31251782, 2019). "Specifically, heme activates phospholipase C gamma (PLC-γ), facilitating the translocation of cleaved gasdermin D (c-GSDMD) to mitochondria, resulting in GSDMD pore formation, mitochondrial dysfunction, and the release of mitochondrial DNA (mtDNA) during bacterial infection." (PMID 40221420, 2025). "Additionally, caspase-8 may also activate GSDMD and promote the maturation of IL1β and IL18, as observed in the context of bacterial infections." (PMID 41173854, 2025). "In neutrophils, activation of canonical caspase-1 inflammasomes or non-canonical caspase-11 inflammasomes also triggers GSDMD-mediated pyroptotic death, which is essential for host protection from extracellular or intracellular and cytosolic bacterial infections." (PMID 38195694, 2024).
bacterial infection (continued). "The findings also increase our understanding of how GSDMD versus GSDME cleavage is differentially utilized for IL-1β secretion and regulated cell death responses in neutrophils compared with macrophages, and in bacterial infections where neutrophils are the predominant cell type." (PMID 37730693, 2023). "Thus, this suggests that GSDMD may have additional, hitherto unknown functions in non-immune cells that contribute to its protective effects against intestinal bacterial infection." (PMID 38807373, 2024).
inflammation (17 papers, 2019 to 2025). Aberrant reaction of the microcirculation characterized by movement of fluid and leukocytes from the blood into extravascular tissues. "In addition, using Gsdmd-deficient mice, we demonstrated that GSDMD is a key player in acute CS-induced lung inflammation." (PMID 36045672, 2022). "In CIA mice, inhibition of NLRP3 or blockade of GSDMD pore formation mitigated joint swelling, reduced bone erosion, and attenuated synovial inflammation." (PMID 41089701, 2025). "The levels of caspase-11, cleaved GSDMD, and IL-1β levels were significantly increased, which contributed to pulmonary inflammation in BLM-stimulated human and rat lung epithelial cells, as well as in BLM-induced pulmonary fibrosis mice." (PMID 39795884, 2024). "Recently, it is shown that GSDMD-dependent pyroptosis is triggered in silica-treated AMs by activating the TLR4/NLRP3/caspase-1/GSDMD pathway, which results in aggravated pulmonary inflammation and diffuses silicon nodules." (PMID 35819638, 2022). "GSDMD participated in cardiac inflammation, and resulted in LPS-induced myocardial injury and cell death, by enriching in mitochondria, leading to mitochondrial dysfunction and overproduction of ROS, further regulating the activation of the NLRP3 inflammasome." (PMID 34820388, 2021). "Therefore, we speculated that GSDMD may induce pyroptosis under the regulation of caspase-1, which may mediate the occurrence and development of renal inflammation and eventually lead to renal function damage." (PMID 35577353, 2022). "Therefore, inhibition of NLRP3 inflammasome and GSDMD could be a potential therapeutic approach for the prevention and therapy of liver inflammation and fibrosis through regulating pyroptosis." (PMID 32071306, 2020). "Collectively, these results suggested that inhibition of GSDMD with DSF could protect mice from lung I/R and attenuate NETs release in pulmonary inflammation." (PMID 37794018, 2023). "Moreover, GSDMD-specific deletion in microglia by using the GSDMDfl/flCx3cr1-CreERT2 mice does not suppress CNS autoimmune inflammation after EAE induction, suggesting that GSDMD in microglia does not play a major role in regulating EAE pathogenesis." (PMID 31467036, 2019).